EGFR (epidermal growth factor receptor)
Diseases named in the same sentence as EGFR in open-access papers (continued):
Sharing a sentence is not in itself a finding about the gene and the disease.
breast carcinoma (continued). "Therefore, the implementation of a standardized protocol may be necessary for future Ethiopian breast cancer studies to accurately assess EGFR status." (PMID 39405290, 2024). "This led us to hypothesize a regulatory role for C/EBP-β, a predominant oncogenic transcription factor in breast cancer, modulated by several receptor tyrosine kinases, such as EGFR, fibroblast growth factor receptor (FGFR), insulin receptor (IR), and IGF-1 receptor (IGF-1R)." (PMID 38560690, 2024). "It is currently unclear whether TRPV3 regulates the progress of breast cancer through EGFR pathway." (PMID 38706904, 2024). "Finally, EGFR−/PDGFRβ− breast cancer MCF7 cells were used as a negative control." (PMID 38532439, 2024). "Other studies also indicated that EGFR could promote ferroptosis in breast cancer and glioblastoma." (PMID 39604837, 2024). "Moreover, EGFR activity is required for TGFβ-induced invasion and migration in breast cancer cells." (PMID 39468555, 2024). "High glucose promoted the proliferation of breast cancer cells through the induction of EGFR activation (EGFR phosphorylation) accompanied by the activation of Rac1 and Cdc42, implying the necessity of Rac1 and Cdc42 in the activation of EGFR following high glucose exposure." (PMID 36984785, 2023). "Target prediction, bioinformatics, molecular docking, and molecular dynamics revealed that the most promising hybrid 4a may exert anti-breast cancer activity by acting on multiple targets such as EGFR, PIK3CA, and MAPK8 and thus participating in multiple tumor-related signaling pathways." (PMID 37928644, 2023). "A possible explanation for this might be found in a study of 198 breast cancers, showing that overexpression of EGFR led to a significantly better response to neoadjuvant chemotherapy and was significantly associated with a higher rate of pathological complete responses." (PMID 36766486, 2023). "However, a recent investigation suggested a co-expression of EGFR and miR-218 in breast cancer." (PMID 37088795, 2023). "Deregulation of apoptosis is a hallmark of all cancer cells, and the agents that activate apoptosis in cancer cells could be valuable anticancer therapeutics; breast cancer cell lines that hyper express the EGFR have been documented to undergo receptor-mediated apoptosis." (PMID 37501139, 2023). "Moreover, the association of ANXA6 with H-Ras-containing protein complexes may contribute to the regulation of EGFR overexpression and p120GAP/Ras assembly in ER (−) breast cancer cells, thereby inhibiting Ras signaling in breast cancer cells." (PMID 37129645, 2023). "Additionally, these bioactive compounds affect cell signaling for cell cycle arrest and survival along with lipid peroxidation, nitric oxide synthase activity, epidermal growth factor receptor, nuclear factor kappa B (NF-κB), and protein kinase C in breast carcinoma." (PMID 37021043, 2023). "Additionally, it has been shown (in breast cancer) that systemic dissemination may lead to internalization and downregulation of EGFR in a metastatic environment leading to resistance to EGFR inhibitors." (PMID 36890818, 2023). "Different hypotheses such as the activation of cell growth signaling pathways like the PIK3A/Akt/mTOR pathway, the overexpression of EGFR or the activation of the RAS-MEK-MAPK pathway have been the subject of research in breast cancer and have led to the development of specific treatments." (PMID 37924026, 2023). "Additionally, one of the gefitinib resistance mechanisms in breast cancer may involve EGFR nuclear translocation." (PMID 37397377, 2023). "EGFR overexpression is observed across all BC subtypes and is higher in the more aggressive TNBC and inflammatory breast cancer (IBC)." (PMID 37537585, 2023). "Furthermore, it could contribute to increased angiogenesis and aggressiveness of malignant mammary tumors, suggesting that EGFR inhibitors could be used to treat metastatic disease." (PMID 37835752, 2023).
breast carcinoma (continued). "Our study for the first time provides evidence that the EGFR system induces in mesenchymal stem cells (MSCs) significant changes in the expression of a wide number of miRNAs, including miR-23c, that might be involved in the cross-talk with breast cancer cells." (PMID 35406622, 2022). "Indeed, this principle has been demonstrated in breast cancer in a recent study that used an EGFR/HER2/VEGFR multi-RTK inhibitor (AEE788) in combination with mTOR rapalogs (rapamycin, temsirolimus, or everolimus) to re-sensitize triple-negative breast cancer cells to mTOR-targeted inhibition." (PMID 35326708, 2022). "Interestingly, it was reported that HIF2α enhances autocrine growth signaling through AREG and EGFR/ErbB4 expression in breast cancer cell lines, strengthening this hypothesis." (PMID 36230857, 2022). "Therefore, we hypothesized that HON could overcome TAM resistance in breast cancer cells by targeting EGFR signaling." (PMID 36601474, 2022). "Breast cancers are classified, inter alia, based on the expression of receptors such as estrogen receptor α (ERα; often referred to as ER), progesterone receptor (PR), and human epidermal growth factor receptor (EGFR; also known as ErbB2/HER2) with tyrosine kinase activity." (PMID 35954312, 2022). "In one case study regarding breast cancer treatment, MOLI used pan-drug datasets targeted at the epidermal growth factor receptor (EGFR) pathway for breast, lung, kidney and prostate cancers and discovered that cetuximab and erlotinib may be useful for treating breast cancer." (PMID 36034741, 2022). "While there were no reports on the association of TROP2 and basal markers in breast cancer, one study of lung adenocarcinoma found that the EGFR mutant was in 54% of the TROP2 low group and 46% of the TROP2 high group, but this was not statistically significant (p = 0.26)." (PMID 36153494, 2022). "In addition, multiple important breast cancer genes were detected in the epigenetic subnetworks, like gene ERBB2 in subnetwork 19, a known proto-oncogene, that encodes HER2, a member of the human epidermal growth factor receptor." (PMID 36418365, 2022). "Consequently, quercetin inhibited the proliferation of human breast cancer cells by upregulating miR-146a expression, inducing apoptosis through caspase-3 activation and mitochondrial-dependent pathways, and by inhibiting invasion via EGFR downregulation." (PMID 35327559, 2022). "Moreover, EGFR demonstrates less sensitivity to Erlotinib (overall effect = 0.16, 95% CI: −0.01 to 0.34, p = 6.52e-02) compared to the breast cancer meta-analyses where not limited to the common cell lines (overall effect = 0.26, 95% CI: 0.16 to 0.36, p = 2.47e-07)." (PMID 36726714, 2022). "Therefore, it might be possible that miR-23c acts as tumor suppressor in TNBC cell lines and that EGFR activation in MSCs contributes to breast cancer progression through the downregulation of such miRNA in the microenvironment." (PMID 35406622, 2022). "However, the efficacy of targeting EGFR as single therapy in breast cancer has been disappointing." (PMID 35992877, 2022). "Alterations in the ErbB family (namely ErbB1 (EGFR/HER1), the orphan receptor ErbB2 (HER2 or Neu), ErbB3 (HER3), and ErbB4 (HER4)) have been associated with BC incidence and poor prognosis and mutations of ErbB effectors are among the most common genetic abnormalities associated with breast cancer." (PMID 36233192, 2022). "Furthermore, ingenuity pathway analysis of TcdB- and TcdBNXN-responsive phosphosites revealed the strong activation of the “HER-2 Signaling in Breast cancer” pathway, confirming the involvement of the EGFR-MAPK pathway in the glucosyltransferase-independent effect." (PMID 35457076, 2022). "Thus, it could be proposed that nano-SiO2 could induce apoptosis in breast cancer cells by disruption of EGFR dimerization, modulation of downstream signaling cascades, and disruption of cellular adhesion, migration, and invasion." (PMID 36559135, 2022).
breast carcinoma (continued). "This helps hospitals that do not test the EGFR mutation status of patients with breast cancer." (PMID 35663041, 2022). "Therefore, Gynura procumbens leaves extract may serve as an alternative therapy in mammary cancer in dogs with high EGFR expression." (PMID 34882994, 2022). "Currently, breast cancer is classified into five major categories (normal-like, luminal A, luminal B, Her2-positive and basal-like) based on expression of three receptors: oestrogen and progesterone hormonal receptors (ER and PR) and the epidermal growth factor receptor ERBB2 (Her2)." (PMID 33845831, 2021). "This may provide new insight into the clinical therapy for breast cancer with overexpressed EGFR." (PMID 33875644, 2021). "PGRMC1 may regulate the proliferation and progression of breast cancer cells, potentially by altering lipid metabolism and by activating key oncogenic signaling pathways, such as ERα expression and activation, as well as EGFR signaling." (PMID 34746100, 2021). "However, until today, targeting EGFR in breast cancer has produced poor therapeutic results indicating possibly the need for better predictive biomarkers relevant to the response to anti-EGFR therapy in breast cancer." (PMID 34828291, 2021). "Notably, the exosome that was injected intravenously could deliver the let-7a miRNA to EGFR-expressing xenograft breast cancer tissue in RAG2(−/−) mice." (PMID 34575511, 2021). "Interestingly, a recent study found that stabilizing EGFR protein promotes breast cancer stemness." (PMID 33995681, 2021). "Examination of the protein–protein co-expression patterns in breast cancer subset, which were determined using information-theoretic surprisal analysis, revealed that EGFR protein could be found in several altered sub-networks that characterized both TNBC and non-TNBC tumors." (PMID 34638492, 2021). "The anti-EGFR aptamer induces selective apoptotic cell death and, upon structural optimization [the use of 2′-O-methyl (2′-OMe) units], its human serum stability and toxic potential are increased in breast cancer, liver cancer, and malignant glioblastoma cells." (PMID 34064412, 2021). "To further determine the mechanisms through which SHP-1 suppresses breast cancer, we focused on EGFR and members of its major downstream signaling pathway to investigate whether they might be responsible for the suppressed proliferation and invasion induced by SHP-1." (PMID 34591414, 2021). "Although a study reported that 11% of TNBC patients harbor EGFR gene mutations 33, other studies indicated that activating mutations in EGFR gene are rare in TNBC 34-36, which may explain the low afficacy of EGFR TKI in unselected breast cancer patients." (PMID 33995681, 2021). "The role of EGFR might be different between normal breast and breast cancer." (PMID 34277608, 2021). "Furthermore, the characterized dependence of ER-negative breast cancer cells on NF-κB and the interaction of RANK-c with EGFR in breast cancer cell lines prompted us to further explore the possibility that RANK-c affects EGFR inhibition by known TKIs (erlotinib and gefitinib)." (PMID 34828291, 2021). "Interestingly, the higher serum ObR levels were found in cats with mammary carcinomas presenting a HER2-positive/ER-negative status (p = 0.0291), as reported for human breast cancer patients, confirming the crosstalk between the leptin/ObR axis and the EGFR downstream signaling pathway." (PMID 33644151, 2021). "Recently, inhibition of Akt-1 has been shown to induce metastasis through EGFR-mediated β-catenin nuclear accumulation in breast cancer cells, suggesting that the concomitant inhibition of Akt-1 and EGFR might be effective to limit the metastatic potential of Akt-1 inhibition." (PMID 34946644, 2021). "In addition to EGFR, other RTKs play a role in breast cancer development and progression." (PMID 34477203, 2021).
breast carcinoma (continued). "In previous study we found the anti-breast cancer effect of betulonic acid, and this study revealed that LF triterpenoids might exert anti-breast cancer effect by directly inhibit multiple protein targets and signaling pathways, especially ErbB4 and EGFR and related pathways." (PMID 33246450, 2020). "Moreover, previous studies also indicated that combined therapy targeting both c-Met and EGFR may be beneficial for the treatment of breast cancer patients." (PMID 32201536, 2020). "Furthermore, the EGFR tyrosine kinases are over-expressed in colorectal, lung and breast cancers." (PMID 33158067, 2020). "PAR1 was reported to transactivate EGFR not only in vascular smooth muscle cells and in cardiac fibroblasts, but also in colorectal and in breast cancers through a variety of different mechanisms, showing that the two pathways can reciprocally influence their activities." (PMID 32672423, 2020). "Similarly, activation of epidermal growth factor receptor (EGFR) leads to an expansion of CD44+/CD24− populations in TNBC (which is heavily enriched in basal-like breast cancer) in a mitogen-activated protein kinase kinase/extracellular signal-regulated kinase (MEK/ERK) dependent manner." (PMID 32391382, 2020). "Breast cancer may be studied by their molecular profile, based on the presence or absence of three receptors: the oestrogen receptor (ER), progesterone receptor (PR) and epidermal growth factor receptor Her2/Neu." (PMID 32872155, 2020). "Magnetic levitated breast cancer (BC) and colorectal cancer (CRC) cells expressed high levels of N-cadherin and epidermal growth factor receptor molecules comparable to BC and CRC xenografts grown in severe combined immunodeficient (SCID) mice." (PMID 33316977, 2020). "S100A6 could be potential target for treating HER2 and EGFR positive breast cancer." (PMID 30736768, 2019). "111In-labelled anti-EGFR mAbs may be a promising alternative for AE-radiotherapy of EGFR-overexpressing breast cancer that would not cause these adverse effects (as discussed in the Preclinical Studies section)." (PMID 31659527, 2019). "Hence, the EGF/EGFR/PKC/MEK/ERK/EGR1/PN1/HtrA1 signaling axis might be a potential therapeutic target for breast cancer treatment." (PMID 31501409, 2019). "Finally, to confirm whether EGFR–c-Src-mediated HDAC3 phosphorylation was critical for the invasion of breast cancer cells, we performed rescue experiment using shRNA-resistant HDAC3 plasmids (rsh-HDAC3)." (PMID 31430896, 2019). "Thus, EGFR activation can be a target for breast cancer treatment as well as MAPK inhibition." (PMID 31772936, 2019). "Thus, a combination of AESN and an EGFR- or VEGFR-suppressing agent might be more beneficial in killing human breast cancer MCF7 cells." (PMID 31835887, 2019). "Therefore, CAPE-pNO2 against the growth and metastasis of breast cancer might be via restraining MMP-2, MMP-9, and VEGFA expression, and these proteins were associated with the EGFR/STAT3/Akt signaling pathway." (PMID 31214503, 2019). "Therefore, UNC5A, ERα, and EGFR could be developed as markers to identify luminal breast cancers with a potential for subtype conversion." (PMID 29720215, 2018). "Therefore, we asked whether MK-2206 enhance breast cancer metastasis via EGFR mediated β-catenin nuclear accumulation." (PMID 30445978, 2018).
breast carcinoma (continued). "Furthermore, (+)-aeroplysinin-1 from sponge displays a strong antitumor effect by blocking the proliferation of EGFR-dependent human breast cancer cell lines MCF-7 and ZR-75-1, while curcuphenol displays a SRC protein kinase inhibition and curcudiola focal adhesion kinase (FAK) inhibition." (PMID 29320389, 2018). "Moreover, quantitative analysis demonstrated that the double knockdown of Sp1 and Smad3 triggered an additive effect on EGFR expression in breast cancer cells but did not cause a synergistic effect." (PMID 29215776, 2018). "Notably, upon exposure to a single 6 Gy dose of whole-body radiation, which is substantially lower than the combined ~45–50 Gy used for localized breast cancer radiotherapy, stromal PTEN-null associated epithelium develops hyperplasia that can be completely prevented with EGFR inhibition." (PMID 30018330, 2018). "To test whether ErbB2 downregulates Irf6 in human ErbB2-positive breast cancer cells, we examined the effect of ErbB2 inhibitors, such as the anti-ErbB2 antibody trastuzumab or the ErbB2/epidermal growth factor receptor small-molecule inhibitor lapatinib, on Irf6 in these cells." (PMID 30545388, 2018). "Moreover, we also examined whether expression of a phosphorylation-mimic PIKfyve S318D mutant in breast cancer cells could induce EGFR degradation." (PMID 30445978, 2018). "Moreover, in a validation study conducted by our group in patients with high-risk early breast cancer, a negative prognostic value of EGFR protein expression was demonstrated for OS and disease-free survival (DFS) in the multivariate analysis." (PMID 30521571, 2018). "In light of the VOPP1 gene location within the 7p11.2 chromosomal region, which contains EGFR, and frequent amplification in several malignancies, including basal-like breast cancers, we investigated whether altered VOPP1 expression was due to gene amplification." (PMID 30285739, 2018). "Therefore, we determined whether the increased phosphorylation levels of EGFR at Tyr1068 and EGFR total protein in Akt1 impaired breast cancer cells was due to the reduction in degradation through inactivating PIKfyve." (PMID 30445978, 2018). "EGFR gene analysis of breast cancer lesion revealed no mutations." (PMID 30453894, 2018). "In conclusion, our findings suggested that actein could inhibit breast cancer cells metastasis, which may act through the inhibition of EGFR/AKT and NF-κB signaling, suppressed cell adhesion to ECM proteins as well as the reduction of ECM degradation and CXCR4 expression." (PMID 30618758, 2018). "Thus, it may be necessary to investigate the chemoresistance mechanism(s) to EGFR TKI for breast cancer patients." (PMID 30497501, 2018). "In the current study, we demonstrate the apoptotic function of EGFR in metastatic breast cancer is dependent on STAT1 and we address the hypothesis that pharmacologic inhibition of MEK1/2 with trametinib will bias EGFR signaling toward a STAT1-dominated, apoptotic signaling pathway." (PMID 30250119, 2018). "Furthermore, the tyrosine kinase inhibitor of EGFR may provide therapeutic benefits by limiting the metastatic potential when Akt1 inhibitor was used to treat breast cancer." (PMID 30445978, 2018). "Studies have shown that patients with high nuclear EGFR levels have poor clinical outcomes in breast cancer, which implies that nuclear EGFR may benefit tumours by helping to evade cell surface EGFR-targeted small molecule inhibitors and therapeutic antibodies." (PMID 29615051, 2018). "Thus, EP4/EGFR cross talk is another mechanism for increased invasiveness in breast cancer cells." (PMID 29596308, 2018). "Besides, the potential role of PTPIP51 in the sensitivity of HER2-positive breast cancer cells to EGFR-targeted TKIs, the selective recruitment to the HER2 receptor points to a specific function of PTPIP51 in the changes of cellular signaling induced by selective HER2 inhibition." (PMID 30139932, 2018).